GUSBP3 (GUSB pseudogene 3)
Gene: Transcribed unprocessed pseudogene on chromosome 5 (69,640,266 to 69,679,193, reverse strand). Ensembl gene ENSG00000253203.
Diseases named in the same sentence as GUSBP3 in open-access papers:
GUSBP3 is named in the same sentence as 1 disease in open-access papers, as found by Europe PMC text mining. Sharing a sentence is not in itself a finding about the gene and the disease. The quoted sentences say what the papers report.
Sepsis (1 paper, 2024). Sepsis is defined as life-threatening organ dysfunction caused by a dysregulated host response to infection. "We performed a Mann-Whitney U test to evaluate the differential expression of the three genes (EIF1AY, APOBEC3B, and GUSBP3) in E. coli- and S. aureus-induced sepsis groups." (PMID 38968271, 2024).